AQP2 (aquaporin 2)
Diseases named in the same sentence as AQP2 in open-access papers (continued):
Sharing a sentence is not in itself a finding about the gene and the disease.
hydrops (3 papers, 2023 to 2026). "Aquaporin 2 expression is elevated in the endolymphatic sac, a site thought to be involved in the development of endolympatic hydrops, which is associated with MD." (PMID 40123419, 2025). "This upregulation is hypothesized to lead to subsequent V2R-cAMP-PKA-AQP2 activation and thus endosomal trapping of AQP2, leading to impaired endolymph absorption and hydrops." (PMID 41598680, 2026). "Since the development of a rodent model of hydrops, it has been believed that vasopressin may also actively participate in Ménière’s disease pathogenesis by altering the endolymph water flow in the inner ear, through involving vasopressin receptor 2 (V2R) and aquaporin 2 (AQP2)." (PMID 36831323, 2023).
injury (3 papers, 2019 to 2024). Damage inflicted on the body as the direct or indirect result of an external force, with or without disruption of structural continuity. "Earlier research has established that AQP1, AQP4, AQP2 and AQP9 are associated with spinal cord injury- or nerve injury-induced nerve pain in rats." (PMID 35324416, 2022).
kidney injury (3 papers, 2012 to 2021). Trauma to the kidney. "In addition, it has been reported that AQP1 levels in the proximal tubule together with AQP2 levels in the collecting duct are decreased in I/R-induced kidney injury, which results in impaired urinary osmolality." (PMID 35280255, 2021). "Therefore, the increase in the number of proliferative cells may result in reduction of the renal expression of AQP1 and AQP2 at a later phase of cisplatin-induced kidney injury." (PMID 30744167, 2019).
kidney stone (3 papers, 2012 to 2025). "Its activation can promote calcium delivery to the distal nephron, acidify urine, and down-regulate aquaporin-2 expression leading to polyuria, reducing kidney stone risk." (PMID 39055046, 2024). "Additionally, STUB1 can indirectly influence kidney stone formation by influencing affecting aquaporin 2 (AQP2), which regulates urine volume and osmolality." (PMID 40245021, 2025).
leptospirosis (3 papers, 2012 to 2022). A contagious bacterial infection caused by spirochetes of the genus Leptospira. "Polyuria or non-oliguric AKI occurring during the first stage of leptospirosis might be another symptom related to the reduced expression of aquaporin 2 (AQP2) and a urinary concentration defect due to resistance of the inner medullary collecting duct to vasopressin." (PMID 35203344, 2022).
ovarian carcinoma (3 papers, 2018 to 2022). A malignant neoplasm originating from the surface ovarian epithelium. "In the present study, we explored the prognostic significance of AQP2 in 1816 ovarian cancer patients by using the KM plotter database." (PMID 29472315, 2018). "AQP2 mRNA expression exhibited a null correlation with OS within all ovarian cancer patients as well as in serous and endometrioid histological subgroups, HR = 1.13 (0.92–1.38), P=0.25, HR = 1.17 (0.93–1.46), P=0.18 and HR = 3.01 (0.31–29), P=0.32, respectively." (PMID 29472315, 2018). "Our results suggest that individual AQPs, except AQP2 and AQP9, are associated with unique prognostic significance and may thus act as new predictive prognostic indicators and potential drug therapeutic target in ovarian cancer." (PMID 29472315, 2018). "Thus, the prognostic value of AQP2 and AQP9 in ovarian cancer needs further exploration." (PMID 29472315, 2018). "In the present study, constitutive expression of AQP2 and AQP9 mRNA showed not any correlation to the prognosis of all ovarian cancer patients, serous ovarian cancer patients, as well as endometrioid ovarian cancer patients." (PMID 29472315, 2018).
pyelonephritis (3 papers, 2019 to 2022). An inflammatory process affecting the kidney. "AQPs are also targets for many diseases, such as pyelonephritis and IgA nephropathy, in which abnormal levels of AQP2 can be detected in the urine, suggesting that AQP2 may be a therapeutic target for this disease." (PMID 35068345, 2022). "Urinary increased excretion of AQP2 was mainly responsible for polyuria in patients with pyelonephritis and IgA nephropathy, suggesting AQP2 may be a treatment target for those diseases." (PMID 30654539, 2019). "Although investigating the mechanism(s) by which pyelonephritis attenuates urine‐concentrating mechanisms is beyond the scope of the current study, preliminary results suggest the urinary concentration defect is due at least in part to down‐regulation of AQP2 gene expression." (PMID 36151614, 2022). "In contrast, urine concentration defect induced by UPEC‐UTI was associated with a nearly 3‐fold reduction in AQP2, but not UT‐A (SLC14A2), gene expression suggesting that pyelonephritis perturbs urine concentrating ability via a distinct mechanism(s)." (PMID 36151614, 2022).
renal carcinoma (3 papers, 2019 to 2022). A carcinoma arising from the epithelium of the renal parenchyma or the renal pelvis. "For example, 2 kidney-specific genes, UMOD and AQP2, were exclusively associated with the adjacent normal tissues from all 3 renal cancer types in training." (PMID 31026023, 2019). "Loss of Aqp2 is also evident in a mice model that developed renal cancer." (PMID 32059438, 2020). "And mechanism studies showed that MIAC inhibits the activation of the EREG/EGFR signaling pathway by direct binding to AQP2 protein, thereby inhibiting renal cancer progression and metastasis in vitro and in vivo." (PMID 36117171, 2022). "Accordingly, it was proved that AQP2 is low expressed in renal cancer and can inhibit the proliferation and migration of kidney cancer cells." (PMID 36117171, 2022). "This indicates that MIAC directly binds to AQP2, and finally plays a role in inhibiting the occurrence and development of renal cancer by inhibiting the expression of EREG and EGFR and the activation of downstream signaling pathways." (PMID 36117171, 2022). "We further explored the specific role of AQP2 in renal cancer through functional experiments." (PMID 36117171, 2022). "This study revealed for the first time the tumor suppressor potential of the lncRNA-encoded micropeptide MIAC in RCC, which inhibits the activation of the EREG/EGFR signaling pathway by direct binding to AQP2 protein, thereby inhibiting renal carcinoma progression and metastasis." (PMID 36117171, 2022). "And our previous work found that AQP2 is highly expressed in HNSCC patients and can promote the HNSCC cell proliferation and migration, but the specific role in renal cancer is unclear." (PMID 36117171, 2022). "The co-immunoprecipitation experiments of renal cancer cells demonstrated that MIAC and AQP2 proteins bound to each other." (PMID 36117171, 2022).
renal fibrosis (3 papers, 2022 to 2025). A final common manifestation of a wide variety of chronic kidney diseases characterized by glomerulosclerosis and tubulointerstitial fibrosis. "In alloxan-induced DN rats, rutin ameliorated renal fibrosis and metabolic acidosis via reducing the metabolic acidosis-related genes aquaporin 2 (AQP2), aquaporin 3(AQP3), and arginine vasopressin receptor 2 (V2R)." (PMID 35408760, 2022).
syndrome of inappropriate antidiuretic hormone (3 papers, 2019 to 2025). "In contrast, AQP2 appears to reflect systemic neuroendocrine responses to injury (e.g., syndrome of inappropriate antidiuretic hormone—SIADH), and AQP9 may contribute to cellular adaptation via lactate and glycerol transport." (PMID 40564125, 2025).
acute myocardial infarction (2 papers, 2015). Necrosis of the myocardium, as a result of interruption of the blood supply to the area. "The aim of the present study was to evaluate the effects of QL on the expression of AQP2 in rats with CHF induced by acute myocardial infarction and to investigate the underlying mechanisms." (PMID 26074997, 2015). "We have previously demonstrated that rats with chronic HF 21 days after myocardial infarction (MI) increased the abundance of the renal water channel aquaporin-2 (AQP2) in the inner medullary collecting ducts (IMCDs)." (PMID 25658446, 2015).
enuresis (2 papers, 2019 to 2024). An elimination disorder characterized by urinary incontinence, whether involuntary or intentional, which is not due to a medical condition and which occurs at or beyond an age at which continence is expected (usually 5 years). "Primary monosymptomatic nocturnal enuresis in children could be associated with reduction of urine excretion of AQP-2 at night." (PMID 38812639, 2024). "Based on this finding, we can interpret the tendency of the children suffering from nocturnal enuresis to exhibit lower concentrations of urine AQP-2 in comparison to healthy subjects." (PMID 38812639, 2024). "However, clinical evidence for an effect of luminal calcium on AQP2-mediated water reabsorption was provided for the first time, in humans (enuretic children), in a study of Valenti and collaborators, demonstrating that urinary AQP2 and calciuria correlate with the severity of enuresis." (PMID 31717830, 2019).
glioblastoma (2 papers, 2018 to 2022). The most malignant astrocytic tumor (WHO grade IV). "To further investigate the sublocalization of AQP2 in glioblastoma cell lines, we performed FS in glioblastoma cell lines." (PMID 30345080, 2018).
interstitial nephritis (2 papers, 2016 to 2019). Inflammation of the renal tubules and supporting tissues of the kidney. "Several mechanisms of persistent damage caused by lithium have been studied in literature and include slow recovery of aquaporin-2 gene expression after lithium cessation, loss of renal medullary osmotic gradient and lithium-induced interstitial nephritis that causes persistent renal insufficiency." (PMID 30921589, 2019).
Kidney Cyst (2 papers, 2023 to 2024). Abnormal fluid filled sac within the kidney, either acquired or congenital. "A more recent report on Tsc1 inactivation in mouse principal cells showed that kidney cysts exhibited a gradual loss of Aquaporin 2 (AQP-2)-positive cells in their epithelium." (PMID 38028758, 2023).
Meniere disease (2 papers, 2016 to 2017). A disease of the inner ear (labyrinth) that is characterized by fluctuating sensorineural hearing loss; tinnitus; episodic vertigo; and aural fullness. "The presence of vasopressin-AQP-2 system in ES epithelia may play important roles in endolymph volume regulation, suggesting that vasopressin-AQP-2 system in the ES would be involved in the development of Meniere’s disease." (PMID 27804084, 2017).
nephrosis (2 papers, 2013 to 2020). Pathological processes of the KIDNEY without inflammatory or neoplastic components. "“Vasopressin escape” is known to occur in nephrosis, possibly due to a decrease in the renal expression of AQP2." (PMID 32560242, 2020).
preeclampsia (2 papers, 2017). Preeclampsia is a hypertensive disorder of pregnancy that is characterized by new-onset hypertension with proteinuria presenting after 20 weeks of gestation, and depending on mild or severe forms may initially present with severe headache, visual disturbances, and hyperreflexia. "AQP2 expression is higher in the placenta of patients with severe preeclampsia than in normal pregnant women." (PMID 29194396, 2017). "Moreover, the positive correlation of the AQP2 level with human chorionic gonadotropin was found in severe preeclampsia." (PMID 29194396, 2017).
Renal artery stenosis (2 papers, 2023 to 2024). The presence of stenosis of the renal artery. "Similarly, another study reported ADCuh was positively correlated with AQP1 and AQP2 expression in a rabbit model of renal artery stenosis." (PMID 38943548, 2024).
renal cell carcinoma (2 papers, 2022 to 2024). "In renal cell carcinoma (RCC), overexpressed micropeptide MIAC significantly reduces the capacity of cells to proliferate and migrate by binding to AQP2 and reducing EREG/EGFR expression in vitro and in vivo." (PMID 39443468, 2024).
Stroke (2 papers, 2022 to 2025). Sudden impairment of blood flow to a part of the brain due to occlusion or rupture of an artery to the brain. "Lower serum AQP2 levels were inversely correlated with 90-day Modified Rankin Scale scores after ICH, but were not correlated with National Institute of Health stroke scale (NIHSS) scores on admission." (PMID 35386692, 2022).
urinary obstruction (2 papers, 2019 to 2025). "In addition, the direct suppression of aquaporin-2 has been observed in animal models of urinary tract obstruction, which might also explain the mechanism." (PMID 31088379, 2019).
Adrenal insufficiency (1 paper, 2010). Insufficient production of steroid hormones (primarily cortisol) by the adrenal glands. "In addition, urine diluting capacity is reduced in hypothyreoidism and adrenal insufficiency with up regulation of AQP2, and urine concentration capacity is reduced in thyrotoxicosis and glucocorticoid excess with down regulation of AQP2." (PMID 20923561, 2010).
brain injuries (1 paper, 2025). "In this review, we present and discuss the findings from clinical and experimental studies on AQP4, AQP2, AQP9, and AQP11 in acute brain injuries." (PMID 40564125, 2025). "Among them, AQP2, AQP4, AQP9, and AQP11 have been implicated in traumatic and non-traumatic brain injuries." (PMID 40564125, 2025).
chronic obstructive lung disease (1 paper, 2017). "This study tested the effect of roflumilast, a selective PDE4 inhibitor approved by FDA for the treatment of chronic obstructive lung disease, and its active metabolite RNO, on AQP2 regulation in the kidney IMCD." (PMID 28108651, 2017).
congenital cataracts (1 paper, 2018). "Loss of function in AQPs may cause congenital cataracts (AQP0), diabetes insipidus (AQP2), and autoantibodies against AQP4 cause the autoimmune demyelinating disease neuromyelitis optica." (PMID 30555637, 2018).
congenital hydronephrosis (1 paper, 2021). Congenital hydronephrosis is a renal urinary disease characterized by distension and dilation of the renal pelvis and calyces secondary to various congenital obstructive malformations of the kidneys and urinary tract that can evolve to renal atrophy. "Selective decrease in urinary AQP2 and increase in PGE2 excretion are associated with post obstructive polyuria in human congenital hydronephrosis." (PMID 33917112, 2021).
Constipation (1 paper, 2025). Infrequent or difficult evacuation of feces. "Rats fed with bacterial cellulose, a naturally occurring DF derived from bacteria, improved constipation symptoms, shortened defecation periods, increased feces weight, and decreased levels of inhibitory neurotransmitters and AQPs (AQP2, AQP3, and AQP4) in comparison to the constipation group." (PMID 40807605, 2025).
gastric cancer (1 paper, 2018). A primary or metastatic malignant neoplasm involving the stomach. "Notably, prognostic evaluation according to histopathology reports revealed that gastric cancer patients with intestinal subtype at stage III with positive AQP2 mRNA were associated with poor survival rate." (PMID 29678898, 2018). "Distinct role of AQP2 expression in cancer patients including gastric cancer remains largely unknown." (PMID 29678898, 2018). "Additionally, from mRNA analysis, AQP2 mRNA expression showed null relation to the prognosis in all gastric cancer patients, clinical stage (stages I, II and IV) of both male and female population." (PMID 29678898, 2018). "In addition, AQP1 and AQP2 mRNA expression in gastric cancer patients with HER2 negative gene were associated with unfavorable OS." (PMID 29678898, 2018). "In addition, AQP10 and AQP5 mRNA expression with positive HER2 and AQP1 and AQP2 mRNA with negative HER2 were associated with poor survival in gastric cancer patients." (PMID 29678898, 2018). "Through HPA database, we observed that AQP2 protein was not expressed, both in normal and gastric cancer tissues." (PMID 29678898, 2018). "In the present analysis, we revealed that AQP2, AQP6, AQP9, and AQP10 proteins were not expressed both in normal and gastric cancer tissues." (PMID 29678898, 2018).
genital warts (1 paper, 2021). "In addition, in terms of molecular targeted therapy prediction, our results show that the increased expression of AQP2 and CLDN19 is associated with the sensitivity to imiquimod, an imidazoline derivative commonly used to treat genital warts." (PMID 34422051, 2021).
head and neck squamous cell carcinoma (1 paper, 2022). A squamous cell carcinoma that arises from any of the following anatomic sites: lip and oral cavity, nasal cavity, paranasal sinuses, pharynx, larynx, and salivary glands. "According to previous studies, we demonstrated by co-immunoprecipitation and yeast two-hybrid experiments that the micropeptide MIAC can directly bind to AQP2 protein, regulate the actin cytoskeleton and inhibit the growth and metastasis of head and neck squamous cell carcinoma cells." (PMID 36117171, 2022).
hematoma (1 paper, 2024). A hematoma is a collection of blood from a vascular structure into an extravascular space. "In the chronic SDH group, AQP2 plasma concentration negatively correlated with the midline shift measured before surgery (Spearman's ρ -0.54; p = 0.017) and positively with hematoma volume change between baseline and 30 h post-surgery (Spearman's ρ 0.627; p = 0.007)." (PMID 38928322, 2024).
hemorrhage (1 paper, 2022). Loss of blood from the vascular compartment to the exterior or into nonvascular body space as a result of rupture or severance of the blood vessels. "AQP2 was partly localized in astrocytes labeled with GFAP and upregulated simultaneously with GFAP in the collagenase-induced hemorrhage rat brain." (PMID 35386692, 2022).
Horseshoe kidney (1 paper, 2025). A connection of the right and left kidney by an isthmus of functioning renal parenchyma or fibrous tissue that crosses the midline. "The primary objective of the present study is to investigate the spatial and temporal expression pattern of KLK6, as well as AQP1 and AQP2, in the cortex of the kidney throughout normal human nephrogenesis and CAKUT: duplex kidneys, horseshoe kidneys, and dysplastic kidneys." (PMID 40428321, 2025). "The primary objective of the present study is to investigate the spatio-temporal expression patterns of KLK6, AQP1, and AQP2 throughout normal human nephrogenesis and congenital kidney and urinary tract (CAKUT) abnormalities: duplex kidneys, horseshoe kidneys, and dysplastic kidneys." (PMID 40428321, 2025).
Hypervolemia (1 paper, 2025). An increase in the amount of intravascular fluid, particularly in the volume of the circulating blood. "The present study also demonstrated upregulation of the V2 receptor along the renal medulla, where it has a key role in hydroelectrolyte control, which possibly allows water reabsorption through its control of aquaporin 2, modulating the hypervolemia produced by the DOCA-salt hypertensive model." (PMID 40089597, 2025).
intracerebral hemorrhage (1 paper, 2024). A cerebrovascular disorder characterized by bleeding into one or both cerebral hemispheres including the basal ganglia and the cerebral cortex. "For example, in a rat model of intracerebral hemorrhage (ICH), researchers found that aquaporin-2 (AQP2), an astrocyte water channel, is a positive regulator of astrocyte activation that promotes IL-1β expression via TLR4/NF-κB." (PMID 38891900, 2024).
ischemic stroke (1 paper, 2025). A stroke disorder caused by obstruction of blood flow to the brain, due to thrombotic (local blood clot formation) or embolic (due to a blood clot or other material traveling from another site) event. "Only one clinical study on AQP2 in ischemic stroke has been conducted." (PMID 40564125, 2025). "Although AQP2 is not a primary aquaporin involved in ischemic stroke, it may contribute to vasopressin-mediated cerebral edema and CSF disturbances following ischemic injury." (PMID 40564125, 2025).